SOX2 (SRY-box transcription factor 2)
Diseases named in the same sentence as SOX2 in open-access papers (continued):
Sharing a sentence is not in itself a finding about the gene and the disease.
gastric cancer (continued). "In gastric cancers, expression of Sox2 correlates with the tumor stage as well as with a poor prognosis." (PMID 32849491, 2020). "For example, poor survival is associated with high expression of OCT4 (protein encoded by POU5F1 gene) in gastric cancer, high expression of NANOG in lung and breast cancer, or high expression of SOX2 in gastric cancer." (PMID 32664372, 2020). "HMGCS1 translocates into the nuclei of gastric cancer cells under stress conditions and binds to and activates Oct4 and SOX-2 promoters." (PMID 32349352, 2020). "In contrast to the tumor types used in our studies, where SOX2 expression correlates with shorter patient survival SOX2 expression in gastric cancer correlates with longer patient survival." (PMID 32998722, 2020). "HMGCS1 elevates the expression levels of the pluripotency genes Oct4 and SOX-2 and contributes to tumorsphere formation ability in gastric cancer cells." (PMID 32349352, 2020). "Knowing that the transcription factors SOX2 and OCT4 promote stemness, our approach was to isolate stem-like cells in human gastric cancer cell lines using a traceable reporter system based on SOX2/OCT4 activity (SORE6-GFP)." (PMID 32093282, 2020). "Although SOX2 has paradoxically had a tumor-suppressor role in gastric tumorigenesis, it marks normal gastric stem cells that can be a potent origin of gastric cancer." (PMID 30700829, 2019). "SOX2 expression labels normal adult gastric stem cells, and SOX2-positive epithelial cells are a potent origin of gastric cancer." (PMID 30700829, 2019). "Our research provided new insights into the transformation of gastric IM after chronic bile acid reflux and SOX2 regulation at the miRNA level which shed new lights in the early prevention of gastric cancer." (PMID 30733645, 2019). "For instance, one study found that SOX2 was increased in gastric cancer, and tumors expressing high levels of SOX2 showed more extensive invasion, higher TNM stages, and worse prognoses." (PMID 30733645, 2019). "SOX2 expression is significantly increased in gastric cancer stem cells and inhibition of SOX2 expression in gastric cancer stem cells can suppress proliferation and induce apoptosis." (PMID 31375149, 2019). "ECM1 promotes tumor metastasis through epithelial–mesenchymal transition (EMT) progression, L Gan demonstrated ECM1 induced SOX2 expression via direct interaction with integrin β4 (ITGB4) in gastric cancer and thus altering gene expression of EMT factors." (PMID 31335317, 2019). "Downregulation of SOX2 is a well-established and frequent event in gastric cancer and is mediated through epigenetic suppression." (PMID 29720137, 2018). "Such as SOX2 can promote tumor tumorigenesis and development in tongue squamous cell carcinoma, osteosarcoma, or gastric cancer through various signaling pathways." (PMID 30186173, 2018). "In this study, the expressions of ALDH1A1 and Sox2 were detected by immunohistochemistry in 122 gastric cancer specimens." (PMID 28046028, 2017). "For at least four cancers, including gastric cancer and squamous cell lung cancer, low SOX2 expression has been reported to correlate with poor prognosis." (PMID 28388544, 2017). "Blocking Sox2 has been shown to reduce gastric cancer cell proliferation, migration, and tumorigenic potential, and impair the cancer stem cell like phenotype." (PMID 28046028, 2017). "In contrast, other studies reported lower SOX2 expression in gastric cancer and its metastatic lesions compared to matched, normal gastric mucosa." (PMID 28388544, 2017). "We found that low-expression of Mel-18 was correlated with poor prognosis and negatively correlated with overexpression of stem cell markers Oct4, Sox2, and Gli1 in 101 gastric cancer tissues." (PMID 27542229, 2016). "CDKN1B, which also induces G1 arrest, is repressed by SOX2 in pancreatic cancer cells and gastric cancer cells." (PMID 26846300, 2016).
gastric cancer (continued). "We also detected the expression of Mel-18, CD44, CD133, Oct4, Sox2, and Gli1 expressions in gastric cancer cells using Western blot assay or QRT-PCR." (PMID 27542229, 2016). "The Sox2 gene is frequently involved in DNA hypermethylation and downregulation of Sox2 in colorectal and gastric cancers results in increased cell proliferation." (PMID 26871472, 2016). "In gastric cancer and non-small cell lung cancer, siRNA-mediated SOX2 knockdown resulted in decreased sphere-forming ability and self-renewal of the CSC population." (PMID 27489349, 2016). "Previous studies have demonstrated that the expression of SOX2 is increased in lung, liver and stomach cancers, and in other tumor tissues, and that it is positively correlated with the clinicopathological stages and degrees of differentiation of Rb." (PMID 25663891, 2015). "5-Aza is a DNA methyl-transferase inhibitor that has been used successfully for targeting miR129-2 in gastric cancer and for epigenetic modification of SOX2 gene in adult malignant glioma cells." (PMID 25987129, 2015). "In some cancers, including breast, colorectal, ovarian and gastric cancers, SOX-2 expression was found to be negatively correlated to patient survival, prognosis and therapy." (PMID 26244167, 2015). "SOX2 expression was significantly correlated with lymph node metastasis and the stage of tumor invasion in gastric cancer." (PMID 28983346, 2015). "Recent studies have shown that SOX2 is aberrantly expressed in several types of tumors, including breast, lung, prostate, ovarian, gastric cancer, and melanomas." (PMID 24828201, 2014). "Studies in gastric cancer using siRNA-mediated SOX2 knockdown, found reduced spheroid colony formation and increased apoptosis within sphere cells, highlighting the importance of SOX2 in self-renewal capacity." (PMID 25114775, 2014). "In the stomach cancers and atrophic gastritis with Helicobacter pylori infection, it has been reported that SOX2 as a SRY-related HMG box protein and AT motif-binding factor 1 (ATBF-1) are associated with the regulation of MUC5AC expression." (PMID 24829572, 2014). "We further demonstrate a molecular mechanism for SOX2 expression in a subset of gastric cancer cases." (PMID 25300947, 2014). "Recently it has been shown that inhibition of SOX2 reduced the proliferation and migration of gastric cancer cells, increased their apoptosis, induced changes in cell cycle in vitro, and reduced their in vivo tumorigenic potential." (PMID 25477962, 2014). "In this study we characterized the expression of the transcription factor SOX2 in gastric cancer and related it with clinicopathological features and differentiation markers namely MUC5AC (gastric marker) and CDX2 and MUC2 (intestinal markers)." (PMID 25300947, 2014). "From the FISH results, combined with the copy-number PCR, which was performed in a larger set of gastric cancer cases, we can conclude that SOX2 locus copy number gain is a frequent event in gastric cancer." (PMID 25300947, 2014). "We showed, for the first time, that SOX2 combined with CDX2 expression profile in gastric cancer segregate patients into different prognostic groups, complementing the clinicopathological information." (PMID 25300947, 2014). "To clarify the frequency of SOX2 locus copy number alterations in gastric cancer, we performed a copy-number PCR using gDNA from 62 gastric cancer cases, using a RNAse P probe located in chromosome 14 as reference." (PMID 25300947, 2014). "In conclusion, we show for the first time that SOX2 together with CDX2 expression profiles in gastric cancer contributes to segregate patients into different prognostic groups, complementing the clinicopathological information." (PMID 25300947, 2014). "It’s important to note that the involvement of SOX2 in cell proliferation has been controversially discussed in colorectal and gastric cancer." (PMID 25114775, 2014).
gastric cancer (continued). "Nuclear SOX2 expression was found in 52% (104/201) of gastric carcinomas and the expression was heterogeneous among and within the tumors." (PMID 25300947, 2014). "Over-expression of miR-126 was found to inhibit placenta-specific 1(Plac1) and further increase the viability of gastric cancer by targeting sex-determining region Y-box 2 (SOX2) as oncogene." (PMID 24312276, 2013). "We found at least one previous study in which a relatively low level of Sox2 expression in gastric cancer correlates with increased invasiveness/metastatic potential." (PMID 23815808, 2013). "Previously, we demonstrated that SOX2 plays important roles in growth inhibition through cell cycle arrest and apoptosis, and that SOX2 expression is frequently down-regulated in gastric cancers." (PMID 21304604, 2011). "We initially examined the proliferation rates of SOX2-expression positive gastric cancer cell lines, MKN45 and HSC43, after transient transfection of Pre-miR-126." (PMID 21304604, 2011). "In this study, we demonstrated that miR-126 decreased the SOX2 mRNA and protein expression levels in gastric cancer cell lines." (PMID 21304604, 2011). "Expression of KRT6A and PLAC1 was significantly changed by both SOX2 over-expression and knockdown, suggesting that SOX2 is the critical regulatory factor for these two genes in gastric cancer cells." (PMID 21304604, 2011). "We next performed microarray analysis after SOX2 over-expression in a gastric cancer cell line, and found that expression of the placenta-specific 1 (PLAC1) gene was significantly down-regulated by SOX2 over-expression." (PMID 21304604, 2011). "In addition, we found that miR-126 expression was inversely correlated with SOX2 expression in certain cultured and primary gastric cancer cells without DNA methylation of SOX2, indicating that aberrant miR-126 expression may be a novel mechanism underlying SOX2 down-regulation in gastric cancer." (PMID 21304604, 2011). "The situation becomes even more complicated by a recent report describing a tumor-suppressive function of SOX2 in gastric cancers and gastric cancer cell lines." (PMID 22070920, 2011). "To generally evaluate the possibility that miR-126 inhibits SOX2 expression, we transfected Pre-miR-126 and Anti-miR-126 inhibitor (Anti-miR-126) into multiple gastric cancer cell lines." (PMID 21304604, 2011). "To further understand the potential effects of miR-126-mediated SOX2 down-regulation on the gene expression change in gastric cancer cells, we first attempted to identify candidate downstream target genes of SOX2." (PMID 21304604, 2011). "siRNA- and miR-126-mediated SOX2 knockdown experiments revealed that miR-126 positively regulated PLAC1 expression through suppression of SOX2 expression in gastric cancer cells." (PMID 21304604, 2011). "Accordingly, in this study, we aimed to find miRNAs that target SOX2 expression in human gastric cancers." (PMID 21304604, 2011). "We previously reported that SOX2 mRNA and protein were expressed in normal gastric mucosae, but frequently down-regulated in human gastric cancer tissues and cell lines, some of which are due to aberrant DNA methylation." (PMID 21304604, 2011). "To further clarify the importance of miR-126-mediated SOX2 down-regulation in gastric carcinogenesis, we attempted to identify downstream target genes of SOX2 in gastric cancer cells." (PMID 21304604, 2011). "Most of these genes also showed changes in their expression after SOX2 over-expression at least in one more gastric cancer cell line among the two to three cell lines we investigated (data not shown)." (PMID 21304604, 2011). "To determine the target genes of SOX2 controlled by miR-126 in gastric cancer cells, we next performed SOX2 knockdown experiments and further screened for candidate target genes." (PMID 21304604, 2011).
gastric cancer (continued). "To assess the relationship between miR-126 and SOX2 expression in gastric cancers, we initially examined SOX2 mRNA and protein levels by RT-PCR and Western blot analysis, respectively, in 10 gastric cancer cell lines without DNA methylation of SOX2." (PMID 21304604, 2011). "We previously reported that SOX2 expression was frequently down-regulated in human gastric carcinoma tissues (about half of the total cases), some of which was due to aberrant DNA methylation (about 16% of the total cases)." (PMID 21304604, 2011). "SOX2 was found to be frequently downregulated in intestinal metaplasia of stomach and gastric cancers." (PMID 20814443, 2010). "On the other hand, when forced to express SOX2, gastric cancer lines were arrested in G1/S transition and undergone apoptosis." (PMID 20814443, 2010). "The association of Sox2 and Cdx2 genes has also been shown in a different system, that of gastric cancer where Sox2 and Cdx1/Cdx2 are inversely related." (PMID 21103067, 2010). "Among the 52 patients with advanced gastric cancers, those with cancers showing SOX2 methylation had a significantly shorter survival time than those without this methylation (P=0.0062)." (PMID 18268498, 2008). "In the present study, we found that expression levels of SOX2 mRNA were frequently downregulated in human gastric cancer cell lines and primary gastric carcinomas." (PMID 18268498, 2008). "To determine SOX2 expression levels, we performed RT–PCR analysis in 10 human gastric cancer cell lines and the normal stomach mucosae." (PMID 18268498, 2008). "We further performed the knockdown of endogenous SOX2 by siRNA in the SOX2-positive human gastric cancer cell lines." (PMID 18268498, 2008). "To perform functional analysis of SOX2, we transiently expressed exogenous SOX2 in two human gastric cancer cell lines (NUGC3 and GCIY) and OUMS37 cells derived from rat gastric epithelia by using an adenovirus system." (PMID 18268498, 2008). "In conclusion, we revealed that SOX2 expression was frequently downregulated in gastric cancers, some of which were due to aberrant DNA methylation." (PMID 18268498, 2008). "To initially study the epigenetic status of SOX2 in gastric cancer cell lines, we used a demethylating agent, 5-aza-2′-deoxycytidine." (PMID 18268498, 2008). "Recently, Sox2 was reported to be silenced by promoter methylation in intestinal-type gastric cancer." (PMID 18190713, 2008). "As there is a dense CpG island in the 5′ and exon regions of SOX2, we analysed DNA methylation status of SOX2 in human gastric cancer cell lines." (PMID 18268498, 2008). "To assess SOX2 expression levels in primary gastric cancer samples, we examined the expression levels of SOX2 mRNA using quantitative real-time RT–PCR in primary gastric carcinoma tissues and corresponding noncancerous mucosae." (PMID 18268498, 2008). "On the other hand, densely methylated clones were observed in the SOX2 downregulated primary gastric carcinoma tissue (case 8Ca)." (PMID 18268498, 2008). "We previously reported that the SOX2 protein is expressed in normal gastric mucosae but downregulated in some human gastric carcinomas." (PMID 18268498, 2008). "We have previously reported that the SOX2 protein level was often reduced in human gastric carcinoma tissues on immunohistochemical analysis." (PMID 18268498, 2008). "The increased rate of mutations in the WNT/APC/β-catenin pathway observed in CDX2-induced gastric cancers with SOX2 suppression may serve to reinforce CDX2 expression in these cancers, as WNT signaling is an inducer of CDX2 transcription." (PMID 40149431, 2025). "The present study revealed that Nrf2 activation regulates SOX2 expression in gastric cancer cells." (PMID 40864800, 2025). "In contrast, in certain specific malignancies such as gastric cancer, SOX2 may instead function as a tumor suppressor." (PMID 39976818, 2025). "Generally, the expression of SOX2 is diminished in gastric cancer." (PMID 39976818, 2025).
gastric cancer (continued). "In conclusion, gastric cancers with CDX2 induction form two distinct groups according to SOX2 expression that could be used for guiding personalized targeted therapies." (PMID 40149431, 2025). "In that case, a clinical translation of CDX2 and SOX2 as biomarkers of potentially targetable sub-sets of gastric cancers would be more straightforward, given that the infrastructure for IHC performance and evaluation exist widely in clinical pathology laboratories." (PMID 40149431, 2025). "Also, NUAK1 can provide the tumor cell with resistance to chemotherapy by upregulating the STAT/GLI1/SOX2 signaling pathway, as indicated by a recent study on gastric cancer." (PMID 41441397, 2025). "However, the two subgroups of CDX2-induced gastric cancers, with SOX2-maintained mRNA expression and SOX2 mRNA suppression showed minimal differences in member proteins of the immune presentation machinery." (PMID 40149431, 2025). "Sox-2 is key to promoting gastric cancer cell proliferation and chemoresistance, thus exploring its regulatory network may uncover mechanisms driving tumor aggressiveness, recurrence, and therapy resistance, offering new targets for treatment." (PMID 40069421, 2025). "Moreover, notum is a carboxylesterase highly expressed in early-stage gastric cancer that has been reported to enhance gastric cancer stemness through Akt/SOX2 signaling." (PMID 40864800, 2025). "The function of Sox-2 in gastric cancer is still being debated." (PMID 40069421, 2025). "Furthermore, it has been demonstrated that SOX2 is a target gene of miR-429 in gastric cancer cells and that miR-429 is connected to cisplatin resistance in cisplatin-resistant gastric cancer cells." (PMID 38957318, 2024). "Moreover, it was identified by a dual luciferase reporter assay that KLF11 binds directly with the promoters of specific gastric cancer stemness-related molecules, including SOX2 and FOXM1." (PMID 38025523, 2023). "HMGCS1 contributes to gastric cancer progression through activating Oct4 and SOX2 promoters." (PMID 36564758, 2022). "SOX2 knockdown inhibited the spheroid formation of gastric cancer cells." (PMID 36661504, 2022). "In addition, CD44, Wnt2, Bmi1, Notch1, Oct4, Sox2, Nanog, C-mys, ABCG2, CXCR4 and other “stemness associated genes” are highly expressed in the CD44+ gastric cancer cell population." (PMID 36316684, 2022). "The increased SOX2 expression is associated with poor patient prognosis in cancers of the oral cavity, esophagus, colorectal, lung, breast, liver and prostate, whereas in gastric cancer, worse clinical outcome is correlated with the diminished SOX2 expression in cancer cells." (PMID 34261507, 2021). "However, other studies reported SOX2 to be downregulated in gastric cancer, and lower SOX2 expression levels contributed to poorer prognosis." (PMID 32144236, 2020). "However, in another study, Sox2 levels were downregulated in gastric cancers in comparison to normal tissue and high Sox2 expression correlated with decreased metastasis and a better prognosis for the patient due to increased p21 levels." (PMID 32849491, 2020). "LncRNA MALAT1 strengthens cell stemness in gastric cancer by enhancing the mRNA stability of SOX2." (PMID 32239639, 2020). "Therefore, CD44, CD133, OCT4 and SOX2 are generally considered as the surface markers of gastric cancer stem cell." (PMID 32788883, 2020). "SOX2 is the independent prognostic marker for gastric cancer." (PMID 30186173, 2018). "In gastric cancer, high expression of SOX2 was found to be associated with decreased rates of lymph node metastasis and better treatment outcome." (PMID 29703178, 2018). "Furthermore, we intended to analyse the association of ECG with the protein expression of the embryonic transcription factors SOX9 and SOX2 both being potential biomarkers for a stem cell like phenotype in gastric cancer." (PMID 29703178, 2018). "Forty-two percent (51/122) of gastric cancer samples showed Sox2 positive expression." (PMID 28046028, 2017).